RNF43 (ring finger protein 43)
Description:
E3 ubiquitin-protein ligase that acts as a negative regulator of the Wnt signaling pathway by mediating the ubiquitination, endocytosis and subsequent degradation of Wnt receptor complex components Frizzled. Acts on both canonical and non-canonical Wnt signaling pathway. Along with RSPO2 and ZNRF3, constitutes a master switch that governs limb specification (By similarity).
Synonyms: FLJ20315; RNF124; DKFZp781H0392; URCC; SSPCS
Tractability: Antibody: its Gene Ontology location is reachable by antibodies, with high confidence; UniProt places it where antibodies can reach, with medium confidence; UniProt predicts a signal peptide or a membrane-spanning region. PROTAC: UniProt records ubiquitination sites on it.
Gene: Protein-coding gene on chromosome 17 (58,353,676 to 58,417,735, reverse strand). Ensembl gene ENSG00000108375.
Subcellular location: Cell membrane; Endoplasmic reticulum membrane; Nucleus envelope
Pathways (Reactome):
Disease: Signaling by RNF43 mutants
Signal Transduction: Regulation of FZD by ubiquitination
Gene Ontology:
Molecular function: frizzled binding; protein binding; ubiquitin-protein transferase activity; ubiquitin protein ligase activity
Biological process: negative regulation of Wnt signaling pathway; protein ubiquitination; ubiquitin-dependent protein catabolic process; Wnt receptor catabolic process; stem cell proliferation
Cellular component: plasma membrane; endoplasmic reticulum membrane; nuclear envelope
Genetic constraint (gnomAD): Loss-of-function variants: 36 observed, 75.2 expected, observed/expected ratio (o/e) 0.48, 90% interval 0.37 to 0.63. The upper end of that interval is the gene's LOEUF score, 0.63, which puts it in group 2 of 6, group 1 being the genes least tolerant of losing a copy. Missense variants: 773 observed, 1,008.7 expected, observed/expected ratio (o/e) 0.77, 90% interval 0.72 to 0.81. Synonymous variants: 347 observed, 390.73 expected, observed/expected ratio (o/e) 0.89, 90% interval 0.81 to 0.97.
Gene-disease validity (ClinGen):
ClinGen rates the evidence that RNF43 causes each of these diseases.
sessile serrated polyposis cancer syndrome (autosomal dominant): Definitive.
Cancer hallmarks: escaping programmed cell death (suppresses); cell replicative immortality (suppresses); suppression of growth (promotes)
Homologues: Orthologues: chimpanzee RNF43 (99% identical), macaque RNF43 (96% identical), rabbit RNF43 (87% identical), pig RNF43 (83% identical), rat Rnf43 (83% identical), dog RNF43 (83% identical), mouse Rnf43 (82% identical), guinea pig RNF43 (67% identical), tropical clawed frog rnf43 (36% identical). Paralogues in human: ZNRF3 (29% identical).
Diseases named in the same sentence as RNF43 in open-access papers:
RNF43 is named in the same sentence as 126 diseases in open-access papers, as found by Europe PMC text mining. Sharing a sentence is not in itself a finding about the gene and the disease. The quoted sentences say what the papers report.
colorectal cancer (77 papers, 2012 to 2026). A primary or metastatic malignant neoplasm that affects the colon or rectum. "Mutations in RNF43 G659fs are frequently found in colorectal cancer, and RNF43 G659fs mutations can bind to p85 and thus enhance p85 ubiquitination, leading to mTOR signaling activating." (PMID 39759114, 2025). "In another 18% of colorectal cancers, Wnt activation is due to Ring Finger Protein 43 (RNF43) mutations, a protein that usually negatively regulates this pathway." (PMID 39859345, 2025). "Mutations in RNF43 are now understood to be present in multiple cancer types; however, they were first identified in colorectal cancer." (PMID 41002577, 2025). "In particular, Elez and collaborators demonstrated that inactivating RNF43 mutations are predictive of response to anti-BRAF drugs in microsatellite-stable (MSS) colorectal cancer patients." (PMID 40735046, 2025). "In colorectal cancers, RNF43 mutation contexts exhibit an ANT relationship with APC truncating mutations, particularly associated with MSI status, i.e., RNF43 mutations are prevalent in MSI-H tumors but APC mutations are relatively enriched in MSS cases." (PMID 39160568, 2024). "Increased sensitivity to MEK inhibitors was confirmed in RNF43‐mutated melanoma and colorectal cancer cells." (PMID 38225722, 2024). "RNF43 is mutated in approximately 15% of endometrial cancer, 12% of stomach cancer, 11% of colorectal cancer, and 7% of pancreatic cancer." (PMID 38260423, 2024). "Several previous studies have identified RNF43 mutations in diverse cancers, such as colorectal cancers, pancreatic ductal adenocarcinoma, gastric cancer, and intrahepatic cholangiocarcinoma." (PMID 37848933, 2023). "The mutations of RNF43 eventually enhance colorectal cancer tumor growth and promote a high recurrence rate in patients." (PMID 37848933, 2023). "We evaluated 88 MSI-H colorectal cancer patients and identified that fs mutations in the driver gene RNF43 were shared neoantigens among patients, as previously reported." (PMID 36732592, 2023). "In this study, the authors show that RNF43 G659fs is an oncogenic colorectal cancer mutation and sensitizes tumor cells to PI3K/mTOR inhibition." (PMID 35676246, 2022). "Recent papers have implicated oncogenic mutations in BRAF and RNF43 in the serrated neoplasia pathway of right-sided colorectal cancer." (PMID 36275468, 2022). "RNF43 mutation was most common in colorectal cancers, followed by esophagogastric and bladder cancers." (PMID 35798829, 2022). "The RNF43 G659fs mutation occurs frequently in colorectal cancer, but its function remains poorly understood." (PMID 35676246, 2022). "Demethylation treatment with azacitidine in HCT116, a colorectal cancer cell line with an RNF43 mutation and comparatively low AXIN2 expression, resulted in increased AXIN2 expression and increased cell death." (PMID 33202731, 2020). "RNF43 mutations, found in ~19% of colorectal cancer cases, are mutually exclusive to APC mutations and considered a prime hallmark of Wnt‐hypersensitive cancer subsets." (PMID 32965059, 2020). "Recent studies have reported the recurrent inactivating mutations of the tumor suppressor gene RNF43 (an E3 ubiquitin ligase that acts as a WNT inhibitor by targeting WNT receptors for degradation) occurring in about 18% of sporadic colorectal cancer patients." (PMID 29652830, 2018). "In MSI colorectal cancers, RNF43 mutation is more frequent in the MLH1me+ than MLH1me− group, whereas APC/β-catenin mutation is more frequent in the latter." (PMID 29652830, 2018). "RNF43 is mutated in several kinds of malignancies, including colorectal cancer, GC, and pancreatic cancer." (PMID 28446252, 2017). "Taken together, RSPO2/3 translocations and RNF43 mutations are enriched in distinct subtypes of colorectal cancer in terms of mismatch repair." (PMID 27338477, 2016). "RNF43 mutation frequency is 79.7% in the MSI subtype of colorectal cancer and 50.7% in the MSI subtype of endometrial cancer." (PMID 27338477, 2016).
colorectal cancer (continued). "Ring finger protein 43 (RNF43) encodes a transmembrane E3 ubiquitin ligase that negatively regulates canonical Wnt signaling and is classically associated with serrated polyposis syndrome and colorectal cancer." (PMID 42196486, 2026). "Additionally, in colorectal cancer, RNF43 mutations have been shown to predict response to combined anti-BRAF/EGFR therapies, further highlighting the therapeutic relevance of this alteration across tumor types." (PMID 40735046, 2025). "In contrast to cancers with APC or other defects in the β-catenin destruction complex, colorectal cancers with RNF43 mutations may retain WNT pathway ligands dependence and may as a result be better targets for porcupine and tankyrase inhibitors." (PMID 40061138, 2025). "Previous studies have reported the clinical significance of RNF43 mutations in colorectal cancer." (PMID 40860811, 2025). "Whether other member of the EGFR family or other receptor tyrosine kinases that are also frequently mutated in CDX2-suppressed colorectal cancers are also targets of RNF43 is currently unknown." (PMID 39452477, 2024). "Moreover, overexpression of RNF43 decreased B‐RAF protein levels in melanoma and colorectal cancer cells containing mutated RNF43 or B‐RAF." (PMID 38225722, 2024). "RNF43 loss-of-function mutations are often detected in MSI-type colorectal cancer, and PORCN inhibitor, which can inhibit ligand-mediated activation of the Wnt/β-catenin cascade, can effectively inhibit the progression of RNF43-mutant cell-derived PDX colorectal cancer in vivo." (PMID 37848933, 2023). "Furthermore, RNF43-mutated colorectal organoids were particularly sensitive to inhibitors of Wnt signaling, suggesting a classical approach to RNF43-mutated colorectal cancer." (PMID 37576596, 2023). "Several reports have demonstrated the presence of RNF43 fs mutations in MSI-H colorectal cancer." (PMID 36732592, 2023). "Previous studies have confirmed the high frequency of RNF43 mutations in colorectal cancer patients, which may play an activating role in the Wnt pathway in colorectal cancer." (PMID 37848933, 2023). "We observed that, similar to the regulation of DNA repair genes, MYBL2 expression was regulated by Wnt signaling in AsPC‐1 orthotopic xenografts, as well as in a pancreatic cancer PDX with an RNF43 mutation, and a colorectal cancer PDX with an R‐spondin translocation." (PMID 33660437, 2021). "Further, in colorectal cancer, RNF43 mutations were found to associate with BRAF V600E mutation." (PMID 34702444, 2021). "Moreover, recent studies have highlighted the importance of R-spondin, Lgr5, and RNF43 in different cancers types, including colorectal cancer, which harbor inactivating mutations on RNF43." (PMID 33126517, 2020). "Ten colorectal cancer cell lines were analysed for presence of an RNF43 and ZNRF3 mutation." (PMID 27661107, 2016). "Interestingly, RNF43 mutations were identified in a subset of pancreatic cancer, cholangiocarcinoma, colorectal cancer, and mucinous ovarian cancer." (PMID 24466159, 2014). "However, the effect of RNF43-mutated in colorectal cancer remains controversial." (PMID 40860811, 2025). "In support of this, COLO-320DM (APC^p.S811*) and DLD-1 (RNF43^X659fs and RNF43^L214M), two colorectal cancer cell lines harboring Wnt pathway alterations, showed greater sensitivity to JPI-547 than to olaparib." (PMID 40959288, 2025). "In our cohort, 30% of patients tested had a co-existing RNF43 mutation, which is consistent with previously reported prevalences in patients with BRAF-mutated colorectal cancers." (PMID 41002577, 2025). "For instance, in colorectal cancer, BRAFV600E mutations often co-occur with RNF43 mutations and infrequently with APC mutations." (PMID 40735046, 2025). "The three other genes of the pathway that are frequently mutated in colorectal cancer samples, RNF43, CTNNB1, and TCF7L2, were also frequently mutated in colorectal cancer cell lines, although less frequently than APC." (PMID 40061138, 2025).
colorectal cancer (continued). "We provide evidence that in human colorectal cancer cells with a hyperactive WNT pathway due to APC mutations, knockout of RNF43 promotes cancer cell growth by activating EGFR signaling." (PMID 38260423, 2024). "Among previously not reported associations with overall survival were mutations in GATA3 and FANCE genes in colorectal cancer, mutations in gene PTPN11 in glioma, and mutations in RNF43, MSH6 and FBXW7 genes in endometrial cancer." (PMID 39277826, 2024). "Patients with colorectal cancer had large frequency of variants in genes APC (50.2%), KRAS (23.2%), BRAF (14.6%), RNF43 (12.3%), and MSH3 (11.3%)." (PMID 39277826, 2024). "Subsequently, we investigated the impact of depleting ZNRF3 or RNF43 on EGFR clearance at the cell surface in mouse embryonic fibroblasts (MEFs) and human cancer cell lines including APC-mutated colorectal cancer cells." (PMID 38260423, 2024). "In colorectal cancer (CRC), ZNRF3 and RNF43 mutations occur frequently and have been mainly associated with the potentiation of WNT signaling." (PMID 38260423, 2024). "An ongoing study is assessing the RXC004-nivolumab combination (NCT049075539) in patients with RNF43- or RSPO-mutated, metastatic, and MSS colorectal cancer following standard treatments." (PMID 39065798, 2024). "To test the effect of RNF43 KO, we utilized HT29, a colorectal cancer cell line that expresses WT RNF43 at a high level but minimal ZNRF3." (PMID 38260423, 2024). "Early publications on RNF43 appeared in 2004 by a Japanese group stating that RNF43 is an oncoprotein highly expressed in colorectal cancer (CRC)." (PMID 39125653, 2024). "We used the human RNF43 WT- or 117fs-overexpressing CT26 (murine colorectal cancer) cell line, as this cell line had low mouse Rnf43 expression." (PMID 36732592, 2023). "It is well acknowledged that ring finger protein 43 (RNF43), an E3 ubiquitin ligase, exerts suppressive effects in various cancers, such as colorectal cancer, gastric cancer, and endometrial cancer." (PMID 36097369, 2023). "Consistent with this, genetic alterations in RNF43 are found in approximately 18% of colorectal cancer (CRC) cases." (PMID 35040131, 2022). "We customized the multigene panel (72 genes) by adding the QIAseq Human Colorectal Cancer Panel (71 genes, DHS-002Z; Qiagen) to the RNF43 gene because the pathogenicity of the RNF43 gene variant has been reported in SLs." (PMID 36419139, 2022). "For colorectal cancer, the author overserved co-occurrence of oncogenic BRAF mutations with mutations in the ubiquitin ligase RNF43." (PMID 36275468, 2022). "It has been proven that RNF43 is overexpressed in colorectal cancer and stimulates cancer cell proliferation." (PMID 36495591, 2022). "These analyses allowed to identify several interesting molecular subgroups (e.g., colorectal cancer with BRAF and RNF43 mutations), however, the limited clinical annotations in the dataset did not allow to further clinically define these subgroups." (PMID 36275468, 2022). "On account of its crucial function in restraining the Wnt/β-catenin signal activity, RNF43 is widely recognized as a tumor suppressor in various cancers, such as gastric cancer, colorectal cancer, and pancreatic carcinoma." (PMID 36319622, 2022). "Several RNF43/ZNRF3 genetic variants have been detected in human malignancies, however recent work in colorectal cancer has highlighted the need to determine which variants are pathogenic." (PMID 35204808, 2022). "It is reported that PSF is capable of regulating proliferation by recruiting E3 Ub ligases, it targets RNF43 and Hakai in colorectal cancer, leading to their ubiquitination and subsequent proteolytic cleavage." (PMID 33573690, 2021). "To investigate this issue, we employed CRISPR/Cas9 to introduce biallelic RNF43 PTCs in SW480 APC‐mutant colorectal cancer cells, in which RNF43 is actively transcribed (Fig EV2A and B)." (PMID 32965059, 2020).
colorectal cancer (continued). "The RNF43 and ZNRF3 mutant colorectal cancer cell lines were all MSI, and all harbour a mutation within the EGFR-MAPK signalling pathway." (PMID 27661107, 2016). "This study provides a comprehensive analysis of RNF43 and ZNRF3 in cohorts of colorectal cancers stratified by BRAF mutation and MSI status." (PMID 27661107, 2016). "We analysed RNF43 and ZNRF3 for mutation, copy number variation and expression in a large number of colorectal cancers stratified for molecular subtype." (PMID 27661107, 2016). "In our earlier study, we found that expression of RNF43 was frequently enhanced in colorectal cancer as well as hepatocellular carcinomas." (PMID 24466159, 2014). "However, a few studies on the relationship between RNF43 and co-mutation characteristics and prognosis, and the clinical significance of RNF43-mutated and other biomarkers such as BRAF and MSI status in colorectal cancer are still worth exploring." (PMID 40860811, 2025). "Furthermore, low RNF43 and AXIN2 levels indicate the involvement of β-catenin activation in inflammatory bowel disease-associated colorectal cancer development." (PMID 41487817, 2025). "Besides frequent deletions in ACC, ZNRF3 and RNF43 are also important tumor suppressors in the more commonly occurring colorectal cancer (CRC); thus, we next analyzed the TCGA colorectal adenocarcinoma (n=629) and CPTAC colon adenocarcinoma (n=110) datasets." (PMID 38260423, 2024). "Interestingly, alternative ubiquitination targets of RNF43 and homologous ligase ZNRF3 at the plasma membrane include EGFR, which is deregulated by pathogenic mutations in a sub-set of CDX2-suppressed colorectal cancers." (PMID 39452477, 2024). "Various conclusions were raised, such as RNF43 being overexpressed in liver cancers, to correlate with gastric and clear cell renal cancer patient survival, or to be lost in a subset of gastric and colorectal cancers." (PMID 37023034, 2023). "However, hyperactivation of Wnt signaling in colorectal cancer results in an elevated expression of RNF43 and ZNRF3." (PMID 37592990, 2023). "Notably, several clinical trials have confirmed the efficacy of RNF43-based immune therapies in colorectal cancer treatment to date." (PMID 37848933, 2023). "Elez et al1 recently showed the novel potential of RNF43 mutations to predict clinical benefit and favorable outcomes in patients with metastatic microsatellite stable (MSS) colorectal cancer (mCRC) and BRAFV600E mutated treated with anti-EGFR/BRAF combinatory regimens." (PMID 36779536, 2023). "In addition to TET1 and RNF43, our study also identified an association between NCOA3, CREBBP, and NOTCH3 mutations and improved survival in colorectal cancer patients." (PMID 35798829, 2022). "Thus, the abnormal expression of RNF43 is related to tumorigenesis, such as pancreatic ductal adenocarcinoma, gastric cancer, and colorectal cancer." (PMID 37304674, 2021). "Furthermore, RNF43 exerts suppressive effects in various cancers, such as colorectal cancer, gastric cancer, and endometrial cancer." (PMID 37304674, 2021). "Thus far, there have been a few attempts to use RING-type ligases as predictive biomarkers and therapeutic targets in treating cancer; RNF43 modulates Wnt signalling and has been used to target colorectal cancer and pancreatic ductal carcinoma." (PMID 32848509, 2020). "Unexpectedly, a recent analysis incorporating a large cohort of patients with colorectal cancer who were treated with immunotherapy, demonstrated that RNF43-mutant tumors responded significantly better to immunotherapy than would have been expected from their mutational burden." (PMID 33202731, 2020). "RNF43 mutations were generally associated with poor outcome in patients with colorectal cancer, regardless of the microsatellite instability phenotype (MSI) status." (PMID 32934222, 2020).